AR (androgen receptor)
Diseases named in the same sentence as AR in open-access papers (continued):
Sharing a sentence is not in itself a finding about the gene and the disease.
prostate carcinoma (continued). "Taken together, our in vitro and in vivo efficacy data demonstrate that targeting p300/CBP proteins for degradation using CBPD-409 represents a promising therapeutic strategy for advanced AR-dependent prostate cancers, while exhibiting minimal on or off-target toxicity." (PMID 38586029, 2024). "These interactions in the defined cavity indicated that this polymer could be an effective anti-prostate candidate, because AR is involved in the growth of prostate cancer cells, and these interactions indicated the inhibition of prostate cancer cell growth." (PMID 38699722, 2024). "AR-positive prostate cancer cells exhibit a distinct chromatin landscape compared to DNPC and NEPC cells, suggesting that GR, at least, may interact with different pioneer factors in these various cancer states." (PMID 39027480, 2024). "This degradation does not affect prostate cancer-derived hinge-domain-deficient AR splicing variants." (PMID 38275816, 2024). "In the androgen-responsive LNCaP prostate cancer cell line, it was found that androgen deprivation or treatment with the anti-androgen bicalutamide (an AR antagonist) led to accumulation of GFP-LC3 puncta and the presence of double- and multi-membrane structures, as assessed by electron microscopy." (PMID 38910881, 2024). "Our study revealed that MED12 and CDK8/19 regulate AR activity and that their inhibition may modulate response to enzalutamide in prostate cancer." (PMID 39253786, 2024). "Indeed, monensin has been previously reported to reduce the expression of AR in prostate cancer cell lines and to synergise with the anti-androgen flutamide." (PMID 38228924, 2024). "Additionally, SOX2, through the JAK-STAT signaling pathway, can facilitate the conversion of AR-dependent prostate cancer cells into a multi-lineage state." (PMID 38778150, 2024). "Conventional androgen deprivation therapy (ADT) targets the androgen receptor (AR) inhibiting prostate cancer (PCa) progression; however, it can eventually lead to recurrence as castration‐resistant PCa (CRPC), which has high mortality rates and lacks effective treatment modalities." (PMID 38946578, 2024). "Improving AR resistance is currently the most important part of prostate cancer research that needs to be addressed, and the development of lncRNA studies related to the AR signaling pathway may help to overcome AR resistance in prostate cancer." (PMID 39655078, 2024). "Another therapy used for prostate cancer is treatment with AR antagonists." (PMID 38958553, 2024). "RAC3 is an important co-activator of androgen receptor, in the prostate, and it may have a significant role in prostate cancer progression." (PMID 38200409, 2024). "DECR1-dependent PUFA remodeling enhances mitochondrial oxidative stress to promote lipid peroxidation and ferroptosis, which is a negatively regulated by androgen receptor, thus suggesting ferroptosis induction by targeting androgen receptor signaling in human prostate cancer." (PMID 38908072, 2024). "In addition, the connection between the androgen receptor (AR) pathway in prostate cancer, mitochondrial dysfunction, and programmed cell death requires further investigation." (PMID 39296545, 2024). "For instance, Glutathione S-transferases (GSTP1) implicating carcinogen defenses, growth-factor-signaling pathways (NKX3.1, PTEN) that regulate the growth and survival of prostate cells, and AR, which is a transcription factor, are critical determinants of prostate cancer phenotype cells." (PMID 39595075, 2024). "C4-2, an AR-positive castrate-resistant prostate cancer cell line, served as a positive control." (PMID 38361046, 2024). "Building upon and complementing TWAS, CWAS utilizes specific cistrome data – like the androgen receptor (AR) and H3K27 acetylation (H3K27ac) in prostate cancer – to assess the impact of SNP alleles on peak intensity, employing methods like LASSO penalized regression or single SNP models." (PMID 39099406, 2024).
prostate carcinoma (continued). "While the binding sites of GR and AR in prostate cancer cells exhibit clear overlap, there seems to be a difference in the composition of enriched motifs: FOXA1 motif enrichment is more prevalent in AR binding sites, whereas ETS family motif enrichment is more prevalent in GR binding sites." (PMID 39027480, 2024). "The predominant DNA-based vaccines for prostate cancer are primarily designed to encode proteins such as Prostatic Acid Phosphatase (PAP), Prostate-Specific Membrane Antigen (PSMA), Prostate-Specific Antigen (PSA), and Androgen Receptor (AR), among others." (PMID 39772046, 2024). "Androgens and androgen receptor (AR) signaling play important roles in the normal prostate and prostate cancer (PCa) development, maintenance, and progression, and as biomarkers for prostate cancer." (PMID 38474045, 2024). "Furthermore, in prostate cancer (PCa), the androgen receptor (AR) and the auxiliary coactivator MED1 can form condensates at SEs sites in androgen-dependent PCa cells, facilitating oncogenic gene transcription." (PMID 38383403, 2024). "The androgen/androgen receptor (AR)-signaling axis plays a central role in prostate cancer (PCa)." (PMID 38500100, 2024). "Similarly, PHF8’s involvement in castration-resistant prostate cancer via the AR signaling axis and its role in promoting HER2-positive breast cancer and melanoma metastasis highlight its significance in tumor progression and therapy resistance." (PMID 38813086, 2024). "Therefore, the regulation of HSP27 and the AR in prostate cancer cells is regarded as a good strategy for successful cancer therapy." (PMID 38474045, 2024). "Since clinical development of these novel agents will occur in the ever-changing treatment landscape, this review will first provide an overview of the current prostate cancer treatment landscape, followed by a comprehensive literature review of drugs that either directly or indirectly target AR-Vs." (PMID 38201308, 2024). "An essential part of tumorigenesis in prostate cancer is the androgen receptor (AR)." (PMID 38398019, 2024). "Specifically, it is argued that most human prostate cancer cells do express AR." (PMID 38607014, 2024). "In another study, Sjöstrom and colleagues (2022) saw that local 5hmC enrichment at enhancers or upstream of transcription start sites of prostate cancer drivers, most notably androgen receptor (AR) and forkhead box protein A1 (FOXA1), correlated with their gene expression." (PMID 39336751, 2024). "For initiation and early progression of primary prostate cancer, several driver mutations or alterations have been described e.g., inactivating SPOP mutations, activating FOXA1 mutations, TMPRRS-ERG fusion, loss of PTEN or AR alterations." (PMID 38704600, 2024). "Therefore, developing new therapeutic tools and identifying novel targets inhibiting AR activation and its regulated network remains an active area of prostate cancer research to block the development and progression of CRPC." (PMID 38605607, 2024). "Furthermore, AR is integral to the development and progression of prostate cancer, with many cancer cells relying on AR signaling for survival and growth." (PMID 39296545, 2024). "Therefore, we used a unique systems pharmacology approach to investigate the broad effects of AR-mediated gene expression changes on prostate cancer from AA and EA men." (PMID 38566104, 2024). "The androgen receptor (AR) in prostate cancer has been reported to promote treatment resistance." (PMID 38572428, 2024). "Importantly, most primary prostate cancer (PCa) cells express the AR, and aberrant activation of AR directly promotes PCa development, growth, and progression." (PMID 39369165, 2024). "It has been discovered that IL-1α and IL-1β might transform AR + PCa cells into AR-PCa cells, leading to castrate-resistant prostate cancer (CRPC) and therapy resistance." (PMID 38745115, 2024).
prostate carcinoma (continued). "In this process, LINC00844 promotes the expression of N-myc downstream regulatory gene 1 (NDRG1), and NDRG1 acts as an AR repressor to inhibit AR expression, and the metastasis and differentiation of prostate cancer cells are also inhibited after the AR signaling pathway is suppressed." (PMID 39655078, 2024). "Future studies will also focus on the role of AR in these models, in both the stroma, the cell-autonomous signaling, and tumor-stroma interactions, even in AR-negative prostate cancer cells, which seem to express higher levels of HLA when compared with AR-positive disease." (PMID 38820127, 2024). "Consequently, patients with advanced prostate cancer often receive therapies to reduce androgen ligands and downregulate the androgen-androgen receptor axis which drives tumor proliferation." (PMID 39526247, 2024). "Prostate cancer-associated long-noncoding RNA 1 (PRNCR1) and PCa gene expression marker 1 (PCGEM1) are highly expressed in CRPC and known to be involved in the AR signaling pathway; however, knockdown of either PRNCR1 or PCGEM1 inhibited the growth of CRPC cells in vivo." (PMID 36902032, 2023). "In addition, a reduced expression of androgen receptor was detected in the prostate cancer cells with the infiltrating mast cells." (PMID 36836690, 2023). "The androgen receptor (AR) plays a central role in the development of prostate cancer." (PMID 38004560, 2023). "However, in the case of prostate cancer stem cells, the androgen receptor negatively regulates their maintenance and self-renewal." (PMID 37894767, 2023). "Finally, exosome-mediated transfer of integrin α2 derived from castration-resistant prostate cancer cells promotes migration and invasion of androgen receptor-positive prostate cancer cells by inducing EMT." (PMID 38255186, 2023). "Therefore, AR appears to play a negligible role in the regulation of ferroptosis in human prostate cancer cells." (PMID 36928314, 2023). "In prostate cancer, androgen receptor (AR) targeting is pivotal." (PMID 37686423, 2023). "Selective androgen receptor degraders (SARDs) could be used in this regard, both in the setting of prostate cancer and HCC." (PMID 37508414, 2023). "These distinct roles for EZH2 in promoting prostate cancer progression, metastasis, and AR independence raise the possibility that it could be a potential therapeutic target in advanced disease." (PMID 37104245, 2023). "Longitudinal monitoring of GR expression in plasma-derived EVs from patients with prostate cancer treated with androgen signaling inhibitors facilitates early detection of acquisition of resistance to androgen receptor signaling inhibition in individual patients." (PMID 37930121, 2023). "Androgen receptor signalingis the driving force for the growthand progression of prostate cancer." (PMID 36844574, 2023). "However, data from us and others suggest that EHMT1/LSD1 can function as activators in AR-negative prostate cancer cell lines, indicating their potential involvement in an AR-independent complex." (PMID 37663929, 2023). "As a hormone regulated malignancy, prostate cancer depends on AR signaling for disease development." (PMID 36893587, 2023). "This approach could induce a strong androgen receptor (AR) gene silencing in a murine model of prostate cancer following intravenous administration." (PMID 36899921, 2023). "LNCaP, an AR‐positive prostate cancer cell line, was used for positive control." (PMID 36951594, 2023). "In prostate cancer cells, the androgen receptor (AR), activated by testosterone binding, may attenuate TGF-β signaling by suppressing TGF-βRII expression." (PMID 37373277, 2023). "One important target for activated Ack1 in prostate cancer cells is the androgen receptor (AR)." (PMID 37662484, 2023). "Furthermore, radiation-induced DNA double-strand lesions in prostate cancer cells activate the AR axis." (PMID 36980735, 2023). "Androgen receptor inhibition is significant in the treatment of prostate cancer." (PMID 37298192, 2023).
prostate carcinoma (continued). "The activation of AR is the driving force of prostate cancer." (PMID 36765659, 2023). "However, its potential impact on androgen receptor (AR) and glucocorticoid receptor (GR) signaling in the treatment of prostate cancer has been largely overlooked." (PMID 37860121, 2023). "Similarly, most AR-targeted drugs are approved in the context of prostate cancer, but are still being studied extensively in the context of breast cancer." (PMID 38067367, 2023). "Targeting HSP70 could be a viable strategy to overcome resistance to androgen receptor signaling inhibitor (ARSI) in advanced prostate cancer." (PMID 36773708, 2023). "In prostate cancer, the histological transformation from AR-dependent adenocarcinoma to AR-indifferent neuroendocrine or small-cell carcinoma is a well-known pathway of lineage plasticity, which might occur as a consequence of ADT." (PMID 36776288, 2023). "Interestingly, in a study where samples from primary prostate cancer and benign prostatic hyperplasia were compared, three AR isoforms were dysregulated, and their opposing expression profiles correlated with disease aggressiveness." (PMID 37264224, 2023). "So, it may prevent the onset of this type of cancer because it indirectly blocks the promoters of two essential genes in the pathogenesis of prostate cancer, including androgen receptor (AR) and prostate-specific antigen (PSA)." (PMID 36926328, 2023). "Androgen receptor (AR) is the primary driver of cellular metabolism that fuels growth and proliferation of prostate cancer cells by controlling expression of enzymes involved in multiple aspects of lipid metabolism, including LD accumulation, autophagy, and production of ROS." (PMID 37874216, 2023). "PROTAC-mediated AR degradation could potentiallyaddress several AR-dependent drug resistance mechanisms characteristicof castration-resistant prostate cancer." (PMID 37191389, 2023). "The AR signaling pathway is crucial to the initiation and development of prostate cancer." (PMID 37152995, 2023). "Indeed, ZFHX3, a unreported susceptibility gene identified in the study, was regulated by androgen in prostate cancer cells, and the relationship between androgen/AR signaling and ZFHX3 modulates prostate cancer development and progression." (PMID 37612283, 2023). "Importantly, many ESRP-regulated exons in prostate cancer cells have reciprocal splicing patterns when prostate cancer cells were stimulated with androgens versus treatment with a drug called Casodex that is used to antagonise the androgen receptor." (PMID 37752235, 2023). "Our study may also prompt investigators to look deeper into select kinases that phosphorylate AR, such as CDK1/5/9, ACK1, SRC, MAPK, as inhibition of these kinases in AR+ prostate cancers may provide patient benefit in combination with AR-targeted agents." (PMID 37456235, 2023). "Interestingly, TMPRSS2 is a key regulator in prostate cancer (PCa) progression which is regulated by androgen receptor (AR) signaling." (PMID 36834705, 2023). "However, approximately 20% of people with prostate cancer progress to castration-resistant prostate cancer (CRPC), a lethal disease that is associated with the emergence of constitutively active AR splice variants." (PMID 38049566, 2023). "Second, we used targeted treatments directed at the androgen receptor (AR), which is intrinsically linked to PI3K pathway signaling in prostate cancer and whereby AR inhibition leads to an up-regulation of AKT activity via suppression of the AKT phosphatase PHLPP." (PMID 37126544, 2023). "In addition, we identified S6K1/β-TRCP mediated degradation of LCMT1 as a mechanism for the restoration of AR signaling in antiandrogen refractory prostate cancer cells." (PMID 37644036, 2023). "In addition, miR-34a attenuates prostate cancer aggressiveness via down-regulating AR and Notch-1, which are highly expressed in prostate cancer." (PMID 36969009, 2023).
prostate carcinoma (continued). "Mitogen-activated protein kinases (MAPKs) are enzymes involved in cellular stress responses, cell differentiation, and cell growth, while they also play a crucial role in regulating androgen receptor signaling in both prostate cancer and normal prostate tissue." (PMID 37627077, 2023). "Androgen receptor (AR) signaling have been frequently targeted for treating prostate cancer (PCa)." (PMID 38089408, 2023). "Radioresistance can be conferred by AR-induced activation of DDR genes in prostate cancer." (PMID 36959798, 2023). "Thus, auraptene-induced AMPK activation apparently suppresses the cell growth of prostate cancer cells via at least three mechanisms, i.e., by inhibiting lipid metabolism, AR, and the mTOR/S6 kinase pathway." (PMID 37958994, 2023). "When used synergistically with the androgen receptor antagonist enzalutamide, it could induce disease remission in a castration-resistant prostate cancer model." (PMID 36770884, 2023). "The androgen receptor (AR), as a steroid hormone receptor, can activate the transcription of androgen target cells in a ligand-dependent manner, and is an important driving factor for the progression of prostate cancer." (PMID 37061523, 2023). "Notably, NLK was observed to actively regulate androgen receptor signaling within prostate cancer cells." (PMID 37627077, 2023). "The androgen receptor (AR) is a critical target in all the clinical stages of prostate cancer." (PMID 37744273, 2023). "The development of prostate cancer is dependent on androgen receptor (AR) signaling." (PMID 37104245, 2023). "Additionally, this group of compounds, named microtubule stabilizing agents, can impede the androgen–androgen receptor complex from moving into the cell nucleus, conquering androgen receptor-containing prostate cancer cell proliferation and metastasis." (PMID 37444418, 2023). "For instance, the N-terminal domain (NTD) of the androgen receptor (AR) may play a major role in gene activation, including the initiation of one aggressive form of prostate cancer: castration-resistant prostate cancer (CRPC)." (PMID 37998041, 2023). "Additionally, a significant positive correlation was observed between CSNK2A1 and AR mRNA levels in prostate cancer." (PMID 36860677, 2023). "In addition to promoting the proliferation of prostate cancer cells, the AR also promotes a luminal differentiation program." (PMID 37440313, 2023). "In addition to increased AR protein levels and transcriptional output, significant reprogramming of the AR cistrome and transcriptome accompanies prostate cancer progression." (PMID 38001678, 2023). "For instance, it was observed that the in vitro, long-term treatment of prostate cancer cells with enzalutamide up to 5 μmol/L induced drug resistance and prolonged AR signaling suppression, as well as the downregulation of the cell cycle, Wnt signaling, and DNA repair pathways." (PMID 37958610, 2023). "Ongoing AR-mediated amino acid metabolism research might provide new therapeutic approaches for the management of prostate cancer." (PMID 37282627, 2023). "Thus, PARPi exploits the dual function of PARP1 in DNA damage repair and AR regulation to suppress multiple pathways critical for prostate cancer cell survival and progression." (PMID 37810962, 2023). "Therefore, we expect that the Di-peptide-modified ZIF-8 system can be applied to the co-delivery of the androgen receptor siRNA and chemotherapeutic agents, which is an option for the treatment of castration-resistant prostate cancer." (PMID 37514059, 2023). "Notably, NE cells lack AR and are thus void of androgen dependence, a precarious feature that becomes accentuated in the carcinogenesis of prostate cancer and ultimately the development of CRPC." (PMID 37191417, 2023). "A potential example is the Androgen Receptor (AR), an established prostate cancer target." (PMID 37224961, 2023).